NUDT11 (nudix hydrolase 11)
Description:
Cleaves a beta-phosphate from the diphosphate groups in PP-InsP5 (diphosphoinositol pentakisphosphate), suggesting that it may play a role in signal transduction. Also able to catalyze the hydrolysis of dinucleoside oligophosphates, with Ap6A and Ap5A being the preferred substrates. The major reaction products are ADP and p4a from Ap6A and ADP and ATP from Ap5A. Also able to hydrolyze 5-phosphoribose 1-diphosphate.
Synonyms: hDIPP3beta; APS1; DIPP3B; FLJ10628; ASP1; DIPP3beta
Tractability: PROTAC: ubiquitination databases record sites on it.
Target class: Enzyme; Hydrolase
Gene: Protein-coding gene on chromosome X (51,490,011 to 51,496,592, reverse strand). Ensembl gene ENSG00000196368.
Subcellular location: Cytoplasm
Subcellular location (Human Protein Atlas): Cytosol
Pathways (Reactome):
Metabolism: Synthesis of pyrophosphates in the cytosol
Gene Ontology:
Molecular function: protein binding; bis(5'-adenosyl)-hexaphosphatase activity; bis(5'-adenosyl)-pentaphosphatase activity; diphosphoinositol-polyphosphate diphosphatase activity; endopolyphosphatase activity; hydrolase activity; pyrophosphatase activity
Biological process: adenosine 5'-(hexahydrogen pentaphosphate) catabolic process; diadenosine hexaphosphate catabolic process; diadenosine pentaphosphate catabolic process; diphosphoinositol polyphosphate metabolic process
Cellular component: cytosol; nucleus; cytoplasm
Homologues: Orthologues: macaque NUDT11 (100% identical), chimpanzee NUDT11 (99% identical), dog NUDT11 (96% identical), mouse Nudt10 (96% identical), mouse Nudt11 (96% identical), rat LOC134484128 (96% identical), rabbit NUDT11 (90% identical). Paralogues in human: NUDT10 (99% identical), NUDT4B (91% identical), NUDT4 (90% identical), NUDT3 (74% identical).
Diseases named in the same sentence as NUDT11 in open-access papers:
NUDT11 is named in the same sentence as 13 diseases in open-access papers, as found by Europe PMC text mining. Sharing a sentence is not in itself a finding about the gene and the disease. The quoted sentences say what the papers report.
prostate carcinoma (4 papers, 2015 to 2023). A carcinoma that arises from epithelial cells of the prostate gland. "NUDT10 and Nudix hydrolase 11 (NUDT11) can promote prostate carcinogenesis and increase prostate cancer susceptibility by being involved in a variety of biological processes and mediating cellular stress responses." (PMID 36732869, 2023). "The mRNA sequencing analysis also reveals that several genes, such as NUDT11, CCNA1, and HNF1B, known to promote prostate cancer progression, are significantly up-regulated in the CIC knock-down PC-3 cells." (PMID 26124181, 2015).
glioma (3 papers, 2022 to 2023). A benign or malignant brain and spinal cord tumor that arises from glial cells (astrocytes, oligodendrocytes, ependymal cells). "In this study, we demonstrate for the first time that the risk scores of NUDT7, NUDT11, and CYFIP2 can be used as independent prognostic factors for gliomas." (PMID 35614925, 2022). "After performing Cox univariate and LASSO Cox regression analyses, we selected three genes (NUDT7, NUDT11, and CYFIP2) to construct a risk score model that stratified glioma patients into low- and high-risk groups." (PMID 35614925, 2022). "The results showed that NUDT7, NUDT11, and CYFIP2 were all protective factors for OS in glioma patients." (PMID 35614925, 2022). "Recently, the effect of m7G RNA methylation regulators on glioma prognosis has been investigated, where three genes (NUDT7, NUDT11 and CYFIP2) have been proposed as promising prognostic biomarkers for gliomas." (PMID 36012529, 2022). "The univariate Cox regression analysis of these genes showed that NUDT7, NUDT11, and CYFIP2 are all protective factors with a hazard ratio (HR) of less than 1 for the OS of glioma patients." (PMID 35614925, 2022).
hepatocellular carcinoma (1 paper, 2025). A malignant tumor that arises from hepatocytes. "Although EIF4E, EIF4G3, NUDT4, and NUDT11 expression levels did not exhibit a statistically significant differential between neoplastic and normal samples, their expression displayed an upward trend in hepatocellular carcinoma (HCC) tissues." (PMID 40485623, 2025).
liver cancer (1 paper, 2023). An epithelial or non-epithelial malignant neoplasm that arises from the liver. "Among the genes associated with the prognosis of liver cancer, the genes associated with shorter survival period are AGO2, DCPS, IFIT5, LARP1, NCBP2, NUDT10, and NUDT16; the genes associated with longevity are EIF4E3, EIF4G3, METTL1, NCBP1, NSUN2, NUDT11, NUDT4, and WDR4." (PMID 36845384, 2023).
myeloma (1 paper, 2015). "It is also noteworthy that the 37 top deregulated genes were enriched for the myeloma “stem cell” gene set, including NUDT11, PKP2, ROBO1, AGAP1, NAP1L3 and EPDR1, indicating that “stemness” may play an important role in determining high risk behavior." (PMID 24913504, 2015). "Notably, six of the top deregulated genes (NUDT11, PKP2, ROBO1, AGAP1, NAP1L3 and EPDR1) were recently identified as “stem cell” genes in myeloma." (PMID 24913504, 2015).
serous ovarian cancer (1 paper, 2021). "Three auto-antibodies, against NUDT11, PVR, and TRIM39, were consistently selective for serous ovarian cancer with individual sensitivities ranging from 14.7% to 32.4% at 96% specificity." (PMID 33672007, 2021).
tumor (12 papers, 2020 to 2025). "Genetic and functional analyses showed that when NUDT11 was inhibited, colony formation of tumor-associated cell phenotypes was significantly reduced and their proliferation/survival capacity was compromised." (PMID 35614925, 2022). "Only EIF4E3, IFIT5, EIF4G3, NUDT16, NUDT10, NCBP3, and NUDT11 showed decreased expression in tumor tissues." (PMID 41406096, 2025). "Genes such as EIF4E3, IFIT5, EIF4G3, NUDT16, NUDT10, NCBP3, and NUDT11 showed lower expression in tumor tissues, whereas other genes were highly expressed." (PMID 41406096, 2025). "Specifically, NUDT11 expression levels were remarkably higher while NUDT10 had remarkably lower levels in tumor tissues." (PMID 36661684, 2022). "An elevated protein expression of EIF4E, EIF4G3, LARP1, METTL1, NCBP1, NUDT4, and NUDT11 was discerned in the carcinoma samples, whereas the WDR4 expression was comparable between the tumor and adjacent non‐tumorous tissues." (PMID 40485623, 2025).
cancer (7 papers, 2012 to 2025). A tumor composed of atypical neoplastic, often pleomorphic cells that invade other tissues. "At present, the exact nature of such susceptibility locus is still uncertain, although NUDT11, the gene most proximal to the rs5945572, has been implicated in such cancer predisposition." (PMID 30863497, 2019). "The role of NUDT11 for conferring a stem cell property and increased risk in cancer should be investigated." (PMID 22860071, 2012). "Interestingly, we identified NUDT10 and NUDT11 to be essential in all three cancer cell lines." (PMID 29142246, 2017). "We found 5 primary regulator genes (EIF4E1B, METTL1, NUDT11, NUDT10 and NUDT4B) were differential expressed in more than 15 cancer types." (PMID 36092891, 2022). "Notably, the expression and potential role of NUDT7, NUDT11, and CYFIP2 in cancer are becoming increasingly important." (PMID 35614925, 2022).
NUDT11 also shares sentences with these, for which no sentence is quoted: infection (2 papers); encephalitozoonosis (1); ovarian carcinoma (1); pancreatic adenocarcinoma (1); thymoma (1).